ABO (ABO, alpha 1-3-N-acetylgalactosaminyltransferase and alpha 1-3-galactosyltransferase)
Diseases named in the same sentence as ABO in open-access papers (continued):
Sharing a sentence is not in itself a finding about the gene and the disease.
Oral ulcer (1 paper, 2022). Erosion of the mucous mebrane of the mouth with local excavation of the surface, resulting from the sloughing of inflammatory necrotic tissue. "In our study, we were not able to prove an association between recurrent oral ulcers and ABO/Rh blood group systems; moreover, we reported epidemiological parameters of this entity in a Lebanese sample for the first time, which belongs to the reported global range." (PMID 35272921, 2022).
pancreatic adenocarcinoma (1 paper, 2014). "As a positive control, we included the pancreatic adenocarcinoma cell line HPAF-II (blood group A Se/Se), which showed high levels of ABO transcripts comparable to control gene GAPDH." (PMID 24454787, 2014).
pancreatic ductal adenocarcinoma (1 paper, 2017). An infiltrating adenocarcinoma that arises from the epithelial cells of the pancreas. "When comparing patient and blood donor ABO allele frequencies, we found only the A1 allele to be associated with significantly higher risk for pancreatic ductal adenocarcinoma (PDAC) (23.8% vs. 17.9%; OR = 1.43, P = 0.018)." (PMID 28556564, 2017). "In conclusion, although the choice of control material involves some particular challenges when studying ABO blood groups as a disease risk factor, our results confirm both a genetic and phenotypic association with pancreatic ductal adenocarcinoma." (PMID 28556564, 2017).
pancreatitis (1 paper, 2024). Inflammation of the pancreas. "We investigated the expression of pancreatitis-associated genes with the ability to act as positive regulators of the IL-6 amplifier; these genes include GGT1, PRSS1, CASR, CTRB1, ABO, SPINK1, and CTRC." (PMID 38806529, 2024).
parasitic intestinal infections (1 paper, 2023). "The high titre of ABO antibodies in Asian and African populations has been suggested to be caused by mosquito bites and parasitic intestinal infections." (PMID 37655148, 2023).
pemphigoid (1 paper, 2016). "Since distribution of ABO genes is different among ethnic and social groups, the aim of this study was to determine any linkage between ABO and pemphigoid in the Iranian population." (PMID 27437000, 2016).
pemphigus vulgaris (1 paper, 2020). Pemphigus is a group of chronic autoimmune skin diseases characterized by blister formations on the outer layer of the skin and the mucous membranes. "The aim of this study was to determine the ABO secretor status in the saliva of patients with pemphigus vulgaris." (PMID 32802553, 2020).
Prediabetes (1 paper, 2018). "It is also of interest to note that the prediction of prediabetes for ESCC-specific morality was hinged on different ABO blood types, as revealed by the interaction analysis of this study." (PMID 30406028, 2018). "In this present study, we aimed to investigate whether prediabetes was interacted with the ABO blood group in the prediction of ESCC-specific mortality among 1,857 normal and prediabetic patients over a 15-year follow-up period." (PMID 30406028, 2018).
psoriasis (1 paper, 2024). An autoimmune condition characterized by red, well-delineated plaques with silvery scales that are usually on the extensor surfaces and scalp. "Based on the GWAS data, further MR analysis and colocalization analysis genetically predicted that AIF1, FCGR3A, NEU1, HSPA1A, TNXB (Tenascin XB), and ABO were associated with psoriasis risk." (PMID 39883516, 2024). "According to this study, NEU1, TNXB, and ABO were also related to psoriasis risk." (PMID 39883516, 2024). "MR analyses unveiled 19 unique circulating proteins that were associated with psoriasis, among which only AIF1, FCGR3A, NEU1, HSPA1A, TNXB, and ABO were the potential proteins that interacted with psoriasis risk after being analyzed with high evidence of colocalization (PP.H4 > 0.9)." (PMID 39883516, 2024). "KO models on FCGR3A and ABO (alpha 1-3-N-acetylgalactosaminyltransferase and alpha 1-3-galactosyltransferase) showed phenotypes such as increased T-cell number, abnormal neutrophil physiology, and aberrant skin morphology suggesting a susceptible role in the pathogenesis of psoriasis." (PMID 39883516, 2024).
rectal cancer (1 paper, 2019). A primary or metastatic malignant neoplasm that affects the rectum. "From this independent cohort, we got the similar conclusion, which further confirmed the ABO blood group is associated with survival in Chinese patients with rectal cancer and the blood type B and O were favourable prognostic factors for patients with rectal cancer." (PMID 31777587, 2019). "In the present study, we investigated the value of ABO blood group in predicting the prognosis of patients who underwent radical surgery for rectal cancer." (PMID 31777587, 2019). "The aim of this study was to assess the role of the ABO blood types in predicting the prognosis of a Chinese population in Northwest China region with curatively resected rectal cancer." (PMID 31777587, 2019). "However, little is known about the relationship between ABO blood group and survival in rectal cancer patients." (PMID 31777587, 2019). "Therefore, the aim of this retrospective analysis was to analyze the relationship between ABO blood type and the survival of rectal cancer patients in a Chinese population in Northwest China region as there is an interpopulation variation for this condition." (PMID 31777587, 2019). "Of note, in tumors of the distal colon, antigens, while undetectable in the adjacent tissues, were expressed in tumor cells 22, 23, thus, a structural change in the ABO antigen may occurs in rectal cancer." (PMID 31777587, 2019).
renal failure (1 paper, 2012). "Results showed that the patients divided into two groups according to 25-OHD level were similar with regard to donor age and gender, percentage of living and deceased donors, the number and locus of HLA mismatch, percentage of ABO mismatch, etiology of renal failure, and duration of dialysis." (PMID 22533967, 2012).
rheumatic disease (1 paper, 2021). "The aim of the present study was to examine whether there is an association between ABO and Rh blood groups and the types of rheumatic diseases." (PMID 34964027, 2021). "Therefore, we sought to determine the association between the ABO and Rh blood groups and the type of rheumatic disease in a cohort of Egyptian patients." (PMID 34964027, 2021). "This study for the first time examined the relationship between rheumatic diseases and ABO and Rh blood groups in 304 patients in Egyptian population and determined whether blood group per se is associated with a specific disease and disease phenotype." (PMID 34964027, 2021).
small cell lung carcinoma (1 paper, 2022). Small cell lung cancer (SCLC) is a highly aggressive malignant neoplasm, accounting for 10-15% of lung cancer cases, characterized byrapid growth, and early metastasis. "And experiment 4 was a logistic analysis between small cell lung cancer and ABO blood group." (PMID 36464709, 2022).
spina bifida (1 paper, 2024). A congenital neural tube defect in which vertebrae are not fully formed. "This study has shown mothers’ ABO blood type to be statistically associated with the lesion level and birthweight of their children with spina bifida." (PMID 39144690, 2024). "In conclusion, maternal ABO blood type was found to be associated with lesion level and birthweight of the child with spina bifida and provides genetically based evidence for the heterogeneity of upper and lower lesions." (PMID 39144690, 2024). "Early research compared ABO and Rh blood types of mothers with a history of spina bifida to various samples of mothers from the general population without such a history." (PMID 39144690, 2024). "For that reason, this descriptive study investigated the relationship between mothers’ ABO and Rh blood types and characteristics of children with spina bifida, including sex, lesion level, birthweight, and presence of shunt." (PMID 39144690, 2024).
spondyloarthropathies (1 paper, 2020). "Although Shinebaum reported associations between ABO antigens of non-secretors and host susceptibility to spondyloarthropathies, the results proved to be false later." (PMID 32764781, 2020).
steatosis (1 paper, 2022). Increased lipid within the cytoplasm of cells. "Strong associations with steatosis were observed for rs2519093 (ABO) [AOR = 8.51 (1.01–71.72), p = 0.049] and rs17710008 (MYCT1) [AOR = 2.75 (1.00–7.57), p = 0.050]." (PMID 36386790, 2022).
Stillbirth (1 paper, 2022). Death of the fetus in utero after at least 22 weeks of gestation. "As early as 1943, Levine identified ABO incompatibility as a cause of early abortions and stillbirths." (PMID 35602516, 2022).
toxocariasis (1 paper, 2019). A parasitic infection caused by worms found in domestic animals. "This resemblance interpreted the high titers of isohemagglutinin in animals with toxocariasis; this is due to reactivity of ABO system with experimental antisera to Toxocara and related parasites of the Ascaris genus." (PMID 31040572, 2019).
infection (89 papers, 2002 to 2026). The state of being infected such as from the introduction of a foreign agent such as serum, vaccine, antigenic substance or organism. "This is consistent with the generally weak or inconsistent associations between ABO type and, by extension, isohemagglutinin production and infection risk in broader contexts." (PMID 41511672, 2026). "In turn, more multilevel, population-adjusted studies are required in future to further elucidate the independent impact of ABO phenotype on infection risk." (PMID 41470170, 2025). "Different blood types within the ABO/Rh blood group system have been shown to be associated with varying susceptibility to pathological states and infections, as well as bacterial colonization tendencies." (PMID 41303137, 2025). "pylori, show affinity for specific ABO antigens, potentially increasing the risk of infection, as observed in individuals with blood type O, who are more susceptible to H." (PMID 40376329, 2025). "The challenges include desensitizing high anti-ABO antibody producers and managing the increased risk of infection and malignancy associated with intensified immunosuppression." (PMID 39006667, 2024). "The relationship between ABO blood group expression and susceptibility to infection by SARS-CoV-2 have been explored by a few groups and recently reviewed." (PMID 36844192, 2023). "The ABO blood groups have been shown to affect human susceptibility to many diseases including infections." (PMID 37375493, 2023). "Specifically, we observed a significant modulation of the fucosyltransferase-encoding gene ABO (enzyme involved in HBGA synthesis) after infection with G9P." (PMID 37515094, 2023). "Several studies have investigated the risk factors predisposing to the infection and reported that the host susceptibility can be linked to the ABO blood group, but the current evidence is controversial." (PMID 35683418, 2022). "The results of this research showed that there is an association between ABO blood grouping and infection with the COVID-19 virus." (PMID 33401440, 2021). "Without experimental demonstrations, the associations between the ABO, Lewis, and Secretor histo-blood group systems and infection by T. gondii weaken." (PMID 34222043, 2021). "This set of events can misinterpret the associations between the infection by T. gondii and ABO, Lewis and Secretor histo-blood group systems." (PMID 34222043, 2021). "Previously, a correlation between ABO polymorphism and susceptibility to infection with SARS-CoV-1 was examined." (PMID 35010301, 2021). "We used observational healthcare data on 14,112 individuals tested for SARS-CoV-2 with known blood type in the New York Presbyterian (NYP) hospital system to assess the association between ABO and Rh blood types and infection, intubation, and death." (PMID 32511586, 2020). "Here, we use observational healthcare data on 14,112 individuals tested for SARS-CoV-2 with known blood type in the New York Presbyterian (NYP) hospital system to assess the association between ABO and Rh blood types and infection, intubation, and death." (PMID 33188185, 2020). "Here, the authors use data from ~14,000 individuals tested for SARS-CoV-2 at a New York City hospital, and find that certain ABO and Rh blood types are associated with infection, intubation, and death." (PMID 33188185, 2020). "Biological markers such as the ABO blood group system were amongst these factors that were proposed to be linked to the variability in the disease course and/or the prevalence of the infection among different groups." (PMID 33330542, 2020). "This defect in secretion of ABO blood group antigens is associated with increased susceptibility to infection and to asymptomatic carriage of some microorganisms." (PMID 21274336, 2010). "Whereas meta-analyses provided evidence that there may be a link between ABO and susceptibility to infection, the link between ABO and severity of the disease appears poorly reliable." (PMID 40370735, 2025).
infection (continued). "However, genetic associations with both the risk of infection and disease severity have been reported for the ABO locus, with the O-group being protective when compared with the other ABO groups." (PMID 36810454, 2023). "This study’s findings favor the hypothesis of the involvement of the ABO blood group system in predisposing to infection with SARS-CoV-2." (PMID 37376577, 2023). "In agreement with previous results, ABO was mainly associated with the risk of infection." (PMID 35708486, 2022). "In addition, previous work has identified associations between ABO blood groups and a number of different infections or disease severity following infections, including SARS-CoV-1, P. falciparum, H. pylori, Norwalk virus, hepatitis B virus,and N. gonorrhoeae." (PMID 32511586, 2020). "Although the ABO blood group has been shown to play an important role in resistance or susceptibility to infections, well-designed studies aimed at defining the relationship of the ABO blood group phenotype or allele frequency and susceptibility to CHIK infection are limited." (PMID 25977691, 2015). "This would suggest that the ABO phenotypes may be associated more with modification of disease severity than with infection risk." (PMID 16916459, 2006). "Our results are supported by a consistent population of analyzed subjects; therefore, they give strength to the hypothesis that suggests the ABO blood type is a useful biomarker to predict the risk of infection and to estimate the dynamics of virus transmission." (PMID 37442822, 2023). "Several hypotheses to explain this observed link between ABO type and risk of infection have been suggested, such as the presence of anti-A and -B antibodies in O individuals and the binding of the receptor-binding domain (RBD) of the viral Spike protein to group A antigens." (PMID 36844192, 2023). "Interestingly, levels of natural anti-glycan IgM, including anti-ABO, decrease with aging, which may contribute to the increased risk of infection in the elderly." (PMID 33499228, 2021). "The nature of the ABO histo-blood antigens has recently been reviewed, and their population genetics and relationship to malaria infection in non-pregnant subjects is consistent with a pivotal role in governing infection risk, with a group O association with protective immunity." (PMID 17683546, 2007). "As T. gondii uses the gastrointestinal tract as a route for infection, and ABO, Lewis, and Secretor histo-blood group carbohydrates are expressed in this organ, a potential biological relationship between them has been proposed." (PMID 41471183, 2025). "We also found 12 genes associated with infection at six loci, including four infection-specific genes (TCF19, ABO, OBP2B, and TLE1)." (PMID 37886583, 2023). "The titre of ABO isoagglutinin declines with age, further observations also regarding the distribution of the infection across the different ages are needed." (PMID 35683418, 2022). "The investigation of potential biological relationships between the infection by T. gondii and the ABO, H, Lewis, and Secretor histo-blood group carbohydrates is attractive." (PMID 34222043, 2021). "As T. gondii uses the gastrointestinal tract as a route for infection, and in this organ, the expression of ABO, Lewis, and Secretor histo-blood group carbohydrates occurs, it is reasonable to suppose some biological relationship between them." (PMID 34222043, 2021). "The ABO blood group was related to past infection (p = 0.023), the RH factor was related to recent infection (p = 0.014), while positivity against SARS-CoV-2 antibodies and recent infection were related with the ABO/RH blood group (p < 0.05)." (PMID 34727874, 2021). "Since then, multiple other studies carried out in other countries have supported an association between ABO type and SARS‐CoV‐2 susceptibility to infection and/or outcomes." (PMID 34124710, 2021).